BEX4 (brain expressed X-linked 4)
Description:
May play a role in microtubule deacetylation by negatively regulating the SIRT2 deacetylase activity toward alpha-tubulin and thereby participate in the control of cell cycle progression and genomic stability. In absence of reductive stress, acts as a pseudosubstrate for the CRL2(FEM1B) complex: associates with FEM1B via zinc, thereby preventing association between FEM1B and its substrates (By similarity).
Synonyms: BEXL1; FLJ10097
Tractability: PROTAC: UniProt records ubiquitination sites on it; ubiquitination databases record sites on it.
Gene: Protein-coding gene on chromosome X (103,215,068 to 103,217,246, forward strand). Ensembl gene ENSG00000102409.
Subcellular location: Cytoplasm, cytoskeleton, spindle pole; Nucleus; Cytoplasm
Subcellular location (Human Protein Atlas): Cytosol; Nucleoplasm
Gene Ontology:
Molecular function: alpha-tubulin binding; histone deacetylase binding; protein binding; molecular function inhibitor activity
Biological process: chromosome segregation; negative regulation of tubulin deacetylation; regulation of cell migration; regulation of cell population proliferation; negative regulation of protein ubiquitination
Cellular component: cytoplasm; cytosol; microtubule; nucleoplasm; nucleus; spindle pole
Homologues: Orthologues: chimpanzee BEX4 (100% identical), macaque BEX4 (97% identical), pig BEX4 (75% identical), dog BEX4 (73% identical), rat Bex4 (61% identical), mouse Bex4 (59% identical), mouse Bex6 (48% identical).
Diseases named in the same sentence as BEX4 in open-access papers:
BEX4 is named in the same sentence as 19 diseases in open-access papers, as found by Europe PMC text mining. Sharing a sentence is not in itself a finding about the gene and the disease. The quoted sentences say what the papers report.
oral squamous cell carcinoma (3 papers, 2016 to 2025). "The functional role of BEX4 in oral squamous cell carcinoma (OSCC) remains unknown." (PMID 27297407, 2016). "BEX4 is reported as a proto-oncogene promoting cancer onset and malignant progression in multiple cancers, including LUAD, glioblastoma multiforme, and oral squamous cell carcinoma." (PMID 41404730, 2025).
glioblastoma multiforme (2 papers, 2023 to 2025). "Current research suggests that in addition to being involved in the regeneration of neuronal axons and regulating the cell cycle, BEX1 is also involved in the proliferation and invasion showed that BEX1 and BEX4 can improve the tumor formation and radio resistance of glioblastoma multiforme cells." (PMID 37745297, 2023).
leukoplakia (1 paper, 2016). A white patch or plaque on a mucous membrane that cannot be characterized clinically or pathologically as any other disease. "The correlation of low BEX4 expression with poor cancer-free survival in leukoplakia patients was more significant than other BEX family members including BEX1, BEX2, NGFRAP1 (BEX3) and BEX5." (PMID 27297407, 2016).
lung adenocarcinoma (1 paper, 2021). A carcinoma that arises from the lung and is characterized by the presence of malignant glandular epithelial cells. "Conversely, a study provided evidence that the correlated expression of BEX1 and BEX4 is associated with lung adenocarcinoma prognosis." (PMID 34576008, 2021).
lung carcinoma (1 paper, 2018). "Immunofluorescence analysis showed that BEX4 overexpression significantly increased the multinucleated cells compared with the control cells, indicating that aberrant expression of BEX4 promotes the aneuploidy formation in lung cancer cells." (PMID 30367032, 2018). "Immunoblotting analysis revealed that PLK1 was overexpressed in 10 of the 11 lung cancer cells, and unexpectedly, 9 of the lung cancer cell lines showed a significant positive correlation between the expression of BEX4 and the expression of PLK1 or CDK1." (PMID 30367032, 2018). "Moreover, BEX4 expression is highly elevated in human lung cancer cells and tissues, and it determines whether cells undergo apoptosis or adapt to aneuploidy induced by microtubule inhibitor treatment." (PMID 30367032, 2018). "Therefore, we examined the relationships between BEX4 expression and PLK1 and CDK1 expression in human lung cancer cells." (PMID 30367032, 2018).
neuroblastoma (1 paper, 2017). Neuroblastoma (NB) is the most common solid, extracranial childhood tumor. "In this study, we report for the first time that, Bex4 and Bex6 genes are re-expressed by curcumin and are associated with apoptotic N2a neuroblastoma cell deaths." (PMID 28145533, 2017). "Role of any Bex gene in neuroblastoma and Bex4 and Bex6 in any cancer is completely unknown." (PMID 28145533, 2017). "Therefore, induction of Bex genes (especially Bex6, Bex1 and Bex4 genes) functions as tumor suppressors at least in N2a neuroblastoma cells and may serve as an alternative for the treatment of neuroblastomas and other cancers with silenced Bex genes." (PMID 28145533, 2017). "However, there is no report on Bex4 expression or function in the field of neuroblastoma." (PMID 28145533, 2017).
oral cancers (1 paper, 2016). "BEX4 functions as tumor suppressor by inhibiting proliferation and growth of oral cancer." (PMID 27297407, 2016).
Oral leukoplakia (1 paper, 2016). A thickened white patch on the oral mucosa that cannot be rubbed off. "Low BEX4 expression was associated with poor cancer-free survival of oral leukoplakia patients (Hazard ratio = 2.76, p = 0.0072)." (PMID 27297407, 2016).
ovarian carcinoma (1 paper, 2015). A malignant neoplasm originating from the surface ovarian epithelium. "Downregulation of Bex4 (also known as Transcription Elongation Factor S-II Protein-Like 7, TCEAL7) results in increased NF-κB activity in ovarian cancer cells." (PMID 25612294, 2015).
cancer (10 papers, 2016 to 2025). A tumor composed of atypical neoplastic, often pleomorphic cells that invade other tissues. "However, the constitutive expression of BEX4 resulted in the severe dysregulation of microtubule dynamics, which are known to be associated with cancer." (PMID 27512957, 2016). "We next tested whether BEX4 expression altered the ability of cells to grow anchorage independently, which is a hallmark of cancer cells." (PMID 27512957, 2016). "This fuels cancer growth but also creates opportunities for treatment with drugs that inhibit BEX4 stabilization." (PMID 30367032, 2018). "They found that cancer cells produce elevated levels of a protein called BEX4 due to a chemical modification that renders this protein more stable." (PMID 30367032, 2018). "Accordingly, these results suggest that the regulation of BEX4 expression provides an attractive anti-cancer strategy." (PMID 27512957, 2016). "In other cancer types, BEX4 was identified as a common GEAR in KIRC, LGG, PAAD, and STAD." (PMID 41404730, 2025). "The regulation of aneuploid transformation by BEX4 may represent a common mechanism through which this gene impacts prognosis across different cancer types." (PMID 41404730, 2025). "Interestingly, data mined from the Cancer Therapeutics Response Portal (CTRP) 37 via GSCA indicate that BEX4 expression negatively correlates with sensitivity to multiple receptor tyrosine kinases (lenvatinib, axitinib, and AZD4547)." (PMID 36118521, 2022). "However, the gain-of-function molecular mechanism of the BEX4 gene in human cancers still needs to be elucidated." (PMID 30367032, 2018). "The brain-expressed X-linked 4 (BEX4) gene has been recently identified as a mediator of microtubule hyperacetylation through sirtuin 2 inhibition and is highly overexpressed in human cancers." (PMID 30367032, 2018). "However, the stabilization of BEX4 by the constitutive expression of PLK1 resulted in severe mitotic defects, which are associated with cancer." (PMID 30367032, 2018). "However, the molecular mechanism of the gain-of-function of the BEX4 gene in human cancers remains unknown." (PMID 30367032, 2018). "According to the firebrowse database, the expression levels of BEX1 and BEX4 were considerably higher in GBM than in other types of cancers, suggesting that BEX1 and BEX4 may play an important role in GBM progression." (PMID 34576008, 2021). "As the stability of BEX4 was regulated by PLK1 activity, we examined whether ectopic expression of BEX4 induces polyploidy in cancer cells." (PMID 30367032, 2018). "Unlike these genes, report on pro-apoptotic role of Bex4 gene is very limited and role of Bex6 genes in any cancers has never been reported." (PMID 28145533, 2017). "Expression of BEX1, BEX2, BEX4, and BEX5 were found to be reduced in different human cancers." (PMID 28083995, 2017).
tumor (9 papers, 2016 to 2025). "Given that lenvatinib plus anti-PD-1 antibody can enhance antitumor activity in HCC by decreasing tumor-associated macrophage 38, 39, targeting BEX4 may further improve the efficacy of the combination therapy." (PMID 36118521, 2022). "Low BEX4 level was associated with advanced stage tumor (p = 0.001)." (PMID 27297407, 2016). "A deeper analysis revealed upregulation of genes involved in tumor suppression (Clca2, Spink5, Igfbp6, Nptx1, Bex4, Gadd45g, Yipf5), immune regulation (IL6ra, Ccl6, Cd81, Cd244a, Cd151, and Gata4), apoptosis, and pyroptosis (Ddit3, Rgs6, and Gsdmsc2/3/4)." (PMID 39946195, 2025). "Further validated in GSE64041, these findings suggested that BEX4 can regulate anti-tumor immunity by modulating TME." (PMID 36118521, 2022). "Although no strong correlation was observed between BEX4 mRNA level and tumor grade or disease stage, significantly differential expression of BEX4 was observed across immune and molecular subtypes of HCC." (PMID 36118521, 2022). "BEX1- and BEX4-mediated YAP/TAZ activation enhanced the tumor formation, growth, and radioresistance of GBM cells." (PMID 34576008, 2021). "Taken together, our results provide evidence showing a putative tumor-suppressing functions of BEX4 in OSCC." (PMID 27297407, 2016). "BEX4-overexpressing CAL27 was implanted into nude mice to evaluate the effects on tumor growth in vivo." (PMID 27297407, 2016). "The functional role of BEX4 on tumor growth was examined using OSCC cell lines and xenograft models." (PMID 27297407, 2016). "In the OSCC tissues, low expression of BEX4 was observed in 53.3 % tumor samples from patients with OSCC, while it was only found in 3.3 % paired normal tissues." (PMID 27297407, 2016). "In the animal model, BEX4-overexpressing xenograft developed from CAL27 cells had a significantly smaller tumor volume and slower growth rate." (PMID 27297407, 2016). "Since axon regeneration processes include the polymerization of microtubules and actin filaments, we hypothesized that alteration in cytoskeleton formation is mediated by BEX1 and BEX4 to accelerate cytoskeleton-mediated tumor progression." (PMID 34576008, 2021). "Taken together, we suggested that BEX4 functions as a novel tumor suppressor gene involved in OSCC." (PMID 27297407, 2016). "In contrast, only 10 % tumor tissues with T1-2 stage displayed low BEX4 expression." (PMID 27297407, 2016). "Given that BEX4 expression was remarkably reduced in our cohort, we hypothesized that BEX4 could possibly play a tumor-suppressing role in OSCC." (PMID 27297407, 2016). "Importantly, BEX4 expression led to significant aneuploidy and increase tumor growth." (PMID 27512957, 2016). "Moreover, 75 % tumor tissues with T3-4 stage exhibited low BEX4 expression." (PMID 27297407, 2016). "Another study found that the expression of BEX1 and BEX4 was upregulated in radiotherapy-resistant GBM cells and enhanced the tumor formation, growth, and radioresistance of GBM cells by activating the YAP/TAZ signaling pathway." (PMID 35860560, 2022). "Therefore, inhibition of BEX4 expression in combination with microtubule destabilizing agent treatment could improve treatment efficacy in terms of inhibiting the proliferation of tumor cells." (PMID 27512957, 2016). "Having established that BEX4 expression was suppressed in OSCC, we hypothesized that BEX4 has a tumor suppressing function in OSCC." (PMID 27297407, 2016). "In fact, BEX4 was highly expressed in 45.5% of the tumor specimens and 54.5% of tumor specimens displayed no or low BEX4 expression (high and low expression were defined as IHC score of ⩾6 and ⩽ 5, respectively)." (PMID 27512957, 2016).
infection (1 paper, 2023). The state of being infected such as from the introduction of a foreign agent such as serum, vaccine, antigenic substance or organism. "On the other hand, the highest ranked down-regulated gene (in pattern IV) across all dpi was Bex2 (brain-expressed X-linked 2), while Bex1 and Bex4 trended similarly downward over the course of infection." (PMID 38107402, 2023).
BEX4 also shares sentences with these, for which no sentence is quoted: adenocarcinoma (1 paper); adenosquamous cell carcinoma (1); glioma (1); hepatocellular carcinoma (1); large cell carcinoma (1); sarcomatoid carcinoma (1); squamous cell carcinoma (1).